TGIF1 (TGFB induced factor homeobox 1)
Diseases named in the same sentence as TGIF1 in open-access papers (continued):
Sharing a sentence is not in itself a finding about the gene and the disease.
leukaemia (2 papers, 2017 to 2020). "We find that loss or haploinsufficiency of Tgif1 accelerates leukaemia development and shortens survival time in mouse models of MLL‐AF9‐induced AML and BCR‐ABL‐induced CML." (PMID 33058427, 2020). "We identified at least 45 genes that were differentially expressed in these two populations—33 of these were up‐regulated and 12 were down‐regulated in Tgif1−/− relative to Tgif1+/+ leukaemia cells." (PMID 33058427, 2020). "Here, we present data showing that in addition to its role in normal HSCs, Tgif1 also affects leukaemia‐initiating cell (LIC) function in AML." (PMID 33058427, 2020). "Our data showed that GFP‐expressing cells appeared earlier and with higher numbers in peripheral blood of mice transplanted with Tgif1−/− leukaemia cells than mice transplanted with Tgif1+/+ leukaemia cells." (PMID 33058427, 2020). "When recipient mice were conditioned with a lower dose of radiation, leukaemia developed with a longer latency; however, Tgif1 genotype still significantly impacted survival." (PMID 33058427, 2020). "As mice transplanted with either Tgif1+/+ or Tgif1−/− HSPCs succumbed to leukaemia with very short latency, the aggressive nature of this leukaemia almost certainly underestimates the impact of Tgif1 loss on survival." (PMID 33058427, 2020). "Our results are well aligned with data showing that enforced expression of TGIF1 decreases human leukaemia cell proliferation, induces terminal differentiation and increases survival in MLL‐AF9 rearranged myeloid leukaemia." (PMID 33058427, 2020). "Moreover, enforced expression of TGIF1 in MLL‐AF9‐transduced leukaemia cells influences transcriptional networks regulated by MEIS1, another TALE family member, while the TGIF1:MEIS1 ratio predicts AML survival." (PMID 33058427, 2020). "To simulate the clinical setting, we transplanted Tgif1+/+ and Tgif1−/−, MLL‐AF9‐transformed‐spleen cells from mice with established leukaemia into sub‐lethally irradiated recipients and treated these mice with cytarabine and doxorubicin chemotherapy as described." (PMID 33058427, 2020). "Taken together, these data may suggest that TGIF1 acts as a prototypical stem cell modifier gene, operating not in the initiation of leukaemia but in disease progression and persistence." (PMID 33058427, 2020).
myeloid leukaemia (2 papers, 2017 to 2020). "To gain insight into the biological and molecular pathways affected by Tgif1 gene loss, we compared global gene expression profiles in Tgif1−/− and Tgif1+/+ myeloid leukaemia cells by unbiased mRNA sequencing." (PMID 33058427, 2020). "Many of those genes inhibited by SID peptide treatment (CD44, TGFβR2, LEF1, TCF7L2, FGF2, FGF5, ID2, PIK3R3) are known as direct TGIF1 targets in myeloid leukemia or embryonic stem cells." (PMID 29179446, 2017).
pancreatic cancer (2 papers, 2017 to 2019). "Our results suggest that Has2/CD44 signaling might be a valid target for patients with TGIF1-deficient pancreatic cancer." (PMID 31109321, 2019). "TGIF1, a suppressor of SMAD and an important homeobox contacting protein that plays a vital role in pancreatic cancer patient's survival is also differentially methylated." (PMID 28423671, 2017).
acute kidney injury (1 paper, 2017). Sudden and sustained deterioration of the kidney function characterized by decreased glomerular filtration rate, increased serum creatinine or oliguria. "The genes TGIF1 and HOXD10 are rarely considered in the pathogenesis of acute kidney injury." (PMID 28335481, 2017).
adenoma (1 paper, 2014). A neoplasm arising from the epithelium. "Elevated levels of two particular Fbxw7 substrates, Klf5 and Tgif1, were found in normal intestine and adenomas of R482Q/+, R482Q/R482Q and Fbxw7−/− mice, but not Fbxw7+/− animals." (PMID 23676439, 2014).
anencephaly (1 paper, 2022). A rare neural tube defect during pregnancy, resulting in the absence of a large portion of the brain and skull in the fetus. "Mutations in or absence of TGIF1 can cause HPE, anencephaly, and pituitary dysplasia." (PMID 35331298, 2022).
Anxiety (1 paper, 2021). Intense feelings of nervousness, tension, or panic often arise in response to interpersonal stresses. "Interestingly, among the anxiety- and depression-related DEGs, we found the upregulation of Bcl3, C3, Gpat3, and Tnf in the AMY as well as the increased expression of Crhr2, Nant, Sar1a, and Tgif1 and the decreased expression of Ier2, Il12a, Nrep, and Tnfrsf25 in the ACC." (PMID 33898422, 2021).
autoimmune disease (1 paper, 2024). A disorder resulting from loss of function or tissue destruction of an organ or multiple organs, arising from humoral or cellular immune responses of the individual to their own tissue constituents. "TBX21 together with TGIF1 are predicted to target TAGAP, that is a known regulator of T cell differentiation and autoimmune diseases." (PMID 39090334, 2024).
bronchiolitis obliterans syndrome (1 paper, 2020). A lung disorder that is mainly associated with chronic allograft dysfunction after lung transplantation and that is characterized by inflammation and fibrosis of bronchiolar walls that reduce the diameter of the bronchioles and result in progressive and irreversible airflow obstruction. "Also, in lung transplant biopsies from patients with bronchiolitis obliterans syndrome, an increase in miR-144 was noted to downregulate TGIF1, thereby elevating TGFβ secretion to contribute to increased fibrosis." (PMID 33414721, 2020).
chronic myeloid leukaemia (1 paper, 2020). "Loss of Tgif1 increases LIC frequency in both acute and chronic myeloid leukaemia mouse models, resulting in earlier disease relapse, reduced survival and treatment resistance." (PMID 33058427, 2020).
diabetic nephropathy (1 paper, 2023). "Yet, there is still limited report on the association between other 5 transcription factor genes (CDC5, FAC1, HFH1, IRF1 and TGIF1) and diabetic nephropathy." (PMID 36978091, 2023).
glioblastoma multiforme (1 paper, 2022). "Furthermore, this study confirmed the effect of TGIF1 on glioblastoma cells through in vitro experiments." (PMID 35569122, 2022).
hepatitis C virus infection (1 paper, 2023). A viral infection caused by the hepatitis C virus. "For example, TGIF1 (TGFB-induced factor homeobox 1) is shown to be up-regulated in patients with hepatitis C virus infection, but down-regulated in fibrotic liver patients." (PMID 37108169, 2023).
Hydrocephalus (1 paper, 2012). Hydrocephalus is an active distension of the ventricular system of the brain resulting from inadequate passage of CSF from its point of production within the cerebral ventricles to its point of absorption into the systemic circulation. "Tgif1 null mice in a C57BL/6 strain background show some growth retardation, and an increased frequency of hydrocephalus and kyphosis (data not shown)." (PMID 22514746, 2012).
intestinal cancer (1 paper, 2026). "In mice complete deletion of Tgif1 reduced tumor burden in an Apc mutant model of intestinal cancer." (PMID 42039629, 2026).
intestinal tumours (1 paper, 2014). "To date, however, no direct assessment has been performed of the effects of Tgif1 mutation on intestinal tumours." (PMID 23676439, 2014).
myopia (1 paper, 2008). "Two genes, TGFB-induced factor homeobox 1 (TGIF) and lumican, have been excluded as candidate genes for high myopia, but they have still been treated as potential candidate genes in several subsequent studies." (PMID 18636116, 2008).
Obesity (1 paper, 2026). Accumulation of substantial excess body fat. "For TGIF1, DNA methylation levels were increased in subcutaneous adipose tissue (N = 219) of children with obesity and correlated with fasting serum insulin concentrations." (PMID 42304432, 2026).
papillary thyroid cancer (1 paper, 2022). "Additionally, the tumor-promoting action of TGIF1 has been discussed in papillary thyroid cancer where downregulation of TGIF1 limits the progression of malignant cells in vitro and suppresses aggressive phenotypes in vivo." (PMID 35578338, 2022).
preeclampsia (1 paper, 2026). Preeclampsia is a hypertensive disorder of pregnancy that is characterized by new-onset hypertension with proteinuria presenting after 20 weeks of gestation, and depending on mild or severe forms may initially present with severe headache, visual disturbances, and hyperreflexia. "TGIF1 and its targets, including ADAM12, WNT3A, and ZNF831, are associated with preeclampsia and pregnancy loss." (PMID 42103736, 2026).
Sepsis (1 paper, 2023). Sepsis is defined as life-threatening organ dysfunction caused by a dysregulated host response to infection. "Five characteristic genes—BCL2A1, CD44, ADGRG1, TGIF1, and ING3—were identified, which enabled the prediction of mortality of sepsis." (PMID 37069215, 2023).
spinal cord injury (1 paper, 2020). Penetrating and non-penetrating injuries to the spinal cord resulting from traumatic external forces (e.g., WOUNDS, GUNSHOT; WHIPLASH INJURIES; etc.).
trigonocephaly (1 paper, 2023). "As a dosage‐sensitive gene, TGIF1 was matched to four neuroimaging phenotypes including hypoplasia of corpus callosum, cavum septum pellucidum, enlarged sylvian cistern, and trigonocephaly." (PMID 36691971, 2023).
uterine cancer (1 paper, 2024). Primary or metastatic malignant neoplasm involving the uterine corpus and/or the cervix. "The heatmap shows hypermethylation in tumor tissue samples (A) and hypomethylation in the normal tissue samples (B), which supports our determination of TGIF1 as a hypermethylated biomarker in uterine cancer." (PMID 38886487, 2024). "CERS3 is a signature gene in cervical cancer, but has no current relationship to uterine cancer, and TGIF1 additionally is considered a significantly mutated gene in cervical cancer." (PMID 38886487, 2024).
cancer (28 papers, 2012 to 2026). A tumor composed of atypical neoplastic, often pleomorphic cells that invade other tissues. "A large number of studies have found that TGIF1 plays a critical biological function in a variety of cancers and that its expression is associated with the enhanced invasion, migration, and metastasis of tumor cells." (PMID 35569122, 2022). "Our data suggest that the loss of TGIF1 expression in cancers is primarily mediated by the hypermethylation of promoter CpG islands of the gene in PDAC." (PMID 31109321, 2019). "A number of cancer-associated genes were found, including TGIF1, VEGFA, RUNX1, and PIM1, as well as others." (PMID 29641996, 2018). "Additionally, GeneMANIA was used to predict the gene regulatory network, revealing a complex interaction network involving several key cancer-associated genes, such as TGIF1, PLD1, and PMSC4." (PMID 40963856, 2025). "Most early induced NF-κB target genes associated with cancers (such as Tgif1,2 and Atf3,4) were also Rel-responsive, indicating that early and late Rel target genes may drive oncogenesis." (PMID 37524800, 2023). "The second one is that the different correlation between EHF and TGIF1 in mRNA expression level and pan-cancer analysis maybe caused by post-transcriptional modification." (PMID 33070167, 2020). "A loss of Fbxw7 and subsequent increase in TGIF1 expression has also been implicated in cancer." (PMID 22335355, 2012). "Our microarray analysis conducted on primary PKTP and PKP PDAC cells demonstrated the top gene candidates regulated by TGIF1 involved in cancer stemness or the prometastatic category might be associated with their roles in mediating EMT and distant metastasis of PDAC." (PMID 31109321, 2019). "Using TIMER2.0 and GeneMANIA, we identified a complex regulatory network involving key cancer-related genes such as TGIF1, PLD1, and PMSC4, which influence the tumor’s ability to evade immune responses and metastasize." (PMID 40963856, 2025). "Transforming growth factor β‐induced factor homeobox 1 (TGIF1) reportedly promotes the pathological processes of various malignant tumors." (PMID 35569122, 2022). "For example, protein disulfide isomerase family A member 4, which is encoded by a gene (PDIA4) whose expression is directly correlated with TGIF1, can disrupt the DNA repair mechanism, thereby promoting the proliferation and metastasis of cancer cells." (PMID 35569122, 2022). "To date, a large number of studies found that TGF‐β‐induced factor homeobox 1 (TGIF1), a transcriptional repressor, plays an important biological role in various cancers." (PMID 35569122, 2022). "In the last decade, increasing evidence established a close coherence of TGIF1 expression with the progression of various cancers." (PMID 34884456, 2021). "The homeodomain protein TGIF1 is a transcriptional repressor playing crucial roles in human development and function and is associated with HPE and various cancers." (PMID 34884456, 2021). "To examine if ELF3, EHF and TGIF1 levels are important in human cancers, we measured mRNA expression of these in LUAD tissues along with their paired adjacent peritumoral tissues." (PMID 33070167, 2020). "Consistent with the findings in cancer cells, Wnt signaling increased Tgif1 expression in osteoblasts." (PMID 30902975, 2019). "Both qRT-PCR and immunoblotting showed that the two shRNAs efficiently decreased TGIF1 expression in the cancer cells." (PMID 29050273, 2017). "Immunohistochemistry analysis showed that knockdown of TGIF1 dramatically decreased cancer cell proliferation, as revealed by Ki67 staining." (PMID 29050273, 2017). "WWTR1 and TGIF1 were also reported to be involved in cancer development in various cancer types." (PMID 36157222, 2022). "Thus, this work will help in the development of anti-cancer drugs for the clinical treatment of TGIF1-related disease." (PMID 34884456, 2021).
cancer (continued). "Other functions impacted by Tgif1 expression included cellular movement (P = 1.99 × 10−9), leukocyte function (P = 3.87 × 10−8), cell death and survival (P = 5.38 × 10−8), myeloid cell function (P = 3.24 × 10−8) and cancer (P = 2.63 × 10−7)." (PMID 33058427, 2020). "As a candidate gene of miR-296-3p, TGIF1 was opted because of its influences on cancers." (PMID 33203425, 2020). "TGIF1 exhibited a strong nuclear signal in almost every cancer cells." (PMID 29050273, 2017). "Furthermore, in the CRC tissue, β-catenin and TGIF1 were significantly upregulated in the nuclei of cancer cells." (PMID 29050273, 2017). "Furthermore, to explore the functions of TGIF1 in regulating cancer stem cell (CSC) properties, we compared the expression levels of stemness transcriptional factors, such as Sox2, Nanog, CD44, Nestin, and CD133, between the TGIF1-deficient PDAC cells and TGIF1-sufficient PDAC cells." (PMID 31109321, 2019). "Moreover, TGIF1 plays an important role in promoting cancer cell proliferation and migration." (PMID 29050273, 2017). "Our pan-cancer analyses from TCGA revealed that aberrant expressions of ELF3, EHF, and TGIF1 are prevalent in a wide spectrum of cancers and high levels of these master TFs are associated with poor patient outcomes." (PMID 33070167, 2020). "In the present study, we propose that Etv1 is a nuclear transcriptional factor suppressed by the TGIF1 repressor, and Etv1 upregulation mediated by TGIF1 ablation confers to increase Has2 activity and activate the HA/CD44 cancer stemness pathway in PDAC." (PMID 31109321, 2019). "Its expression has been shown to have a growth-promoting effect in various cancer types, while TGIF1 is not present in OncoKB or the Cancer Gene Census." (PMID 40694850, 2025). "This study provides a structural insight into the binding of TGIF1 with SIN3A, improves the knowledge of the structure–function relationship of TGIF1 and its homologs and will help in recognizing an undiscovered SIN3A-PAH2 binder and developing a peptide inhibitor for cancer treatment." (PMID 34884456, 2021). "We demonstrated that TGIF1 inactivation promotes KrasG12D-driven pancreatic tumorigenesis and that TGIF1 ablation has tumor-promoting effects and activates the HAS2/CD44 cancer stemness pathway, a potent regulator in the induction of TAM polarization, which enhances PDAC distant metastasis." (PMID 31109321, 2019). "In contrast to cancer cells, absence of Tgif1 in bone or osteoblastic cells did not change the basal activity of the Wnt pathway in vitro or in vivo." (PMID 30902975, 2019). "Despite this, TGIF1 expression is significantly higher in cancer than in normal." (PMID 42039629, 2026). "In addition, non-CPG cancer-driver genes with validated CUVs include TGFBR2 and TGIF1 that are also very likely CPG candidates." (PMID 32778766, 2020).